CD4 (CD4 molecule)
Diseases named in the same sentence as CD4 in open-access papers (continued):
Sharing a sentence is not in itself a finding about the gene and the disease.
T-cell leukemia (54 papers, 2005 to 2025). A malignant disease of the T-lymphocytes in the bone marrow, thymus, and/or blood. "The expression of CD4 protein in T-cell malignancies aids in diagnosing certain types of T-cell leukemia and determining leukocyte differentiation and classification." (PMID 37736548, 2023). "The MT2 cell line is an adult T-cell leukemia (ATL) cell line with aberrant CD4 expression established by co-culture of normal human cord leukocytes with leukemic cells from ATL patients." (PMID 34162832, 2021). "Although all mice showed signs of myeloproliferative disease, ~ 40% of the M-KrasG12D mice also developed T-cell leukemia, as determined by presence of CD4 and CD8 double-positive T cells along with enlarged thymuses (data not shown)." (PMID 30323311, 2019). "Most animals in both groups succumbed to a myeloid disease; however, both groups did demonstrate the emergence of T cell leukemia in a small number of mice, indicated by elevated levels of CD4+;CD8+ cells in the bone marrow and spleen." (PMID 29156682, 2017). "Pediatric CD4+/CD8+ T-cell leukemia was represented by 3 CEM clones: two sensitive, CEM-C7–14 and CEM-C1–6, and one resistant, CEM-C1–15, to Dex." (PMID 18045478, 2007). "Fra-2 enhances CCR4 expression in adult T-cell leukemia, and HTLV-1 viral factor-generated GATA3 stimulates CCR4 expression in CD4+ T cells." (PMID 35222362, 2022). "The phenotype of T cell leukemia in lck-distal tax transgenic mice displayed CD4+, CD8+, or CD4+CD8+ (DP) T cells." (PMID 23483782, 2013). "We then stably transfected the non-Treg CD4+ T cell leukemia cell line, E6 Jurkat cells, with IL37 and found significant induction of the Treg phenotype." (PMID 36010641, 2022). "On the other hand, IL-37 expression was minimal or undetectable in the non-Treg CD4+ T cell leukemia cell line, Jurkat cells, prompting us to use Jurkat cells to study biological changes after IL-37 overexpression." (PMID 36010641, 2022). "A previous study reported that higher PTTG1 expression could be found in the CD4+ and CD8+ T lymphocytes of adult T-cell leukemia patients than that of healthy subjects, which implied an intimate association between PTTG1 and lymphocytes." (PMID 35768832, 2022). "Positioned at the center of the SN-Treg signaling network, IL16 can attract CD4+ T cells and inhibit CD3-mediated lymphocyte activation and proliferation, and recombinant human IL16 has shown inhibitory effects on the growth of human T-cell leukemia Jurkat cells." (PMID 38054018, 2023). "We transduced the non-Treg CD4+ T cell leukemia cell line, E6 Jurkat cells, with lentivirus made from an IL37 overexpressing vector (IL37 OE) and demonstrated the induction of Treg-like phenotype and function in IL37 OE Jurkat cells, compatible to human primary Treg cells." (PMID 36010641, 2022). "Intriguingly, while HTLV-1 infects both CD4+ and CD8+ T cells and induces the clonal expansion of both cell types, the vast majority of ATL cases are CD4+ T cell leukemia, suggesting that some CD8+ T cell-specific factors could restrict the leukemogenic potential of HTLV-1 in this cell type." (PMID 35893677, 2022). "Furthermore, restoration of A20 in miR-125b-overexpressing cells decreased the CD4-negative population in T cell leukemia, and decreased glucose uptake and oxygen consumption to the basal level of T cells transfected with vector." (PMID 27637078, 2016). "We found that the chromatin structures in some CTCL cases are closer to myeloid cells rather than CD4+T cells, though CTCL is conventionally classified as T-cell leukemia." (PMID 39746113, 2025). "The PIM family does not alter T-cells and was negative for T-cell markers CD4 and CD8, suggesting that the PIM kinases did not induce a T-cell leukemia in this model system." (PMID 25238262, 2014). "Leukemic cells from both groups of mice expressed variable levels of CD4, CD8, CD24, and CD25 cell surface markers, characteristic of bona fide TEL-JAK2 T-cell leukemia (data not shown)." (PMID 18596915, 2008).
chronic hepatitis B (53 papers, 2008 to 2025). "Taken together, these data suggested that modulation of IL-6R expression on CD4+ T cells is an important mechanism underlies the enhanced Th17 responses in patients with chronic hepatitis B." (PMID 21639870, 2011). "This study examined whether the frequency of CD4+CXCR5+ TFH cells could be associated with active immunity in chronic hepatitis B (CHB) patients." (PMID 21750724, 2011). "To validate whether enhanced IL-6R expression on CD4+ T cells is causative of elevated Th17 response in patients with chronic hepatitis B, we studied the effect of blockade of IL-6R signaling on PMA/ionomycin and HBcAg induced IL-17 production by purified CD4T cells in vitro." (PMID 21639870, 2011). "In this review, we will zoom in on what is known about CD4+ T cells in acute and chronic hepatitis B infection and the importance and opportunities of including CD4+ T cells in antigen-specific T cell-directed therapy to cure cHBV." (PMID 34066322, 2021). "After blocking PD-L1 and LAG-3, CD4+ T cell function in chronic hepatitis B patients was partially restored." (PMID 31390978, 2019). "CD3 and CD4 cells are important T immune cells, they play an important role in chronic hepatitis B, hepatic infections, and immunosuppression." (PMID 31673279, 2019). "After blocking PD-L1 and LAG-3, the function of CD4+ T cells in chronic hepatitis B patients can be partially restored." (PMID 31390978, 2019). "It was reported that circulating CXCR5+CD4+ T cells were expanded in patients with chronic hepatitis B and high frequency of circulating CXCR5+CD4+ T cells were associated with HBeAg seroconversion through IL-21 production manner." (PMID 27447555, 2016). "For patients with CD4 count below 50 (n = 11), 36% (n = 4) patients had chronic hepatitis B infection (based on +ve Core Ag and -Cve HBSAb)." (PMID 23390470, 2013). "The findings from our study are expected to open new avenues for treatment of chronic hepatitis B based on induction of the beneficial CD4+ T cell subtypes by combining antiviral agents and specific T-cell stimulators or suppressors." (PMID 22570512, 2012). "The data in this study indicated that telbivudine is able to differentially influence the CD4+ T-cell subsets in patients with chronic hepatitis B infection." (PMID 22570512, 2012). "In addition, analysis of MM revealed a significantly lower MM of CD4+CD8+T cells in the chronic hepatitis B group (0.8641 ± 0.3966) compared to the normal healthy control group (1.173 ± 0.5620), with a statistically significant difference (p=0.0088)." (PMID 39650657, 2024). "Interestingly, the percentages of CXCR5+CD4+ T cells were greater in the HBeAg - positive chronic hepatitis B group than in the HC group (p < 0.05)." (PMID 24655429, 2014). "There is limited data about the association of SNPs in the Il-16 gene sequence and risk of chronic hepatitis B infection, whereas the role of cellular immunity in dealing with hepatitis HBV infection is clear and on the other hand CD4 (receptor of Il-16) is involved in this process." (PMID 25692036, 2014). "Since CD4 T cells are instrumental for overcoming experimental chronic infection and have been shown to be associated with clearance of chronic hepatitis B in patients, the concomitant induction of anti-viral CD8 and CD4 T cell immunity may be critical for vaccine efficacy." (PMID 34835264, 2021). "We examined the expression of CCR4 on different subsets of T cells including CD4 and CD8 in chronic hepatitis B (CHB) patients and compared it with HBV-vaccinated healthy controls (Vacc-HC)." (PMID 37081509, 2023). "Therapeutic vaccination based on synthetic long peptides (SLP®) containing both CD4+ and CD8+ T cell epitopes is a promising treatment strategy for chronic hepatitis B infection (cHBV)." (PMID 37781393, 2023). "Investigations have revealed their suppressive roles in controlling the antiviral CD4+ and CD8+ T cells in chronic Hepatitis B/C, and HSV-1 infection." (PMID 35720399, 2022).
chronic hepatitis B (continued). "The results showed that compare normal subjects and chronic hepatitis B patients, HBV-ACLF patients had significantly increased white blood count, CD4+ T cells and decreased lymphocytes, CD3+ T cells, and Treg cells." (PMID 33592861, 2021). "The percentages of MDSCs, IFN-γ-producing CD4 and CD8 T cells in the peripheral blood of HCC patients, chronic hepatitis B (CHB) patients, and healthy controls (HC) were determined by flow cytometry." (PMID 32258134, 2020). "After 48 weeks of oligo fucoidan supplementation, the proportion of CD3+CD4+ and CD3+CD8+ cells increased in chronic hepatitis B patients." (PMID 31991892, 2020). "The interaction between TIM-3 and Gal-9 acts to limit the extent of CD8+ T cell immunity to HSV infection and over-expression of TIM-3 on CD4+ and CD8+ T cells correlates with diseases progression in chronic hepatitis B infection." (PMID 25180498, 2014). "The CD4+CD25high Treg frequency in peripheral blood of ACLF and chronic hepatitis B (CHB) patients was measured by flow cytometry." (PMID 22978653, 2012). "Level of circulating CD4+CD25+CD127- Tregs in HCC patients was significantly lower than that in healthy donors and patients with chronic hepatitis B infection before surgery, but was increased after surgery." (PMID 22272696, 2012). "One patient had concomitant hepatitis E and chronic hepatitis B. Thirteen of 15 patients had a median CD4+ T cell count of 156 cells/μL (range, 55–375 cells/μL), and 2 patients did not receive a CD4+ T cell count test." (PMID 37254144, 2023). "The CD4+ T cells in the peripheral blood of patients with chronic hepatitis B also showed high levels of expression of p35 and EB13 protein, indicating that IL-35 was related to the immune response of chronic hepatitis B patients." (PMID 28794689, 2017). "Previous studies reported the enrichment of CD161+CD4+ T cells in the liver during chronic hepatitis, and IFN-γ could facilitate liver fibrogenesis by CD161+CD4+ T cells through the IL-23/IL-17 axis in chronic hepatitis B virus infection." (PMID 35558087, 2022). "Our patients with MDhi CD4 TEM and memory CD8 T cells exhibited functional exhaustion with reduced production of pro-inflammatory cytokines such as TNFα and IFNγ, which was also in line with other reports on chronic hepatitis B or long-term tumor antigen exposure." (PMID 35095881, 2021). "We found that the mean fluorescence intensity (MFI) and frequency of BTLA expression in peripheral blood CD4+ T cells (but not on CD8+ T cells) were significantly upregulated in patients with HBV-ACLF compared with NC and patients with chronic hepatitis B (CHB)." (PMID 38418488, 2024).
coronary artery disease (52 papers, 2005 to 2025). "Moreover, soluble CD14 levels correlated with mortality during the chronic phase of HIV infection, with baseline CD14 levels associated with a more rapid decline in CD4 cells and a higher risk of death from coronary heart disease." (PMID 40565155, 2025). "CD4+CD28null T cells have been directly implicated in the pathogenesis of coronary artery disease." (PMID 16207339, 2005). "In addition, the prognostic cohorts ranged from outpatients with coronary artery disease to inpatients with multiple comorbidities, which may have affected the way of the association (e.g., CD4/CD8 ratio)." (PMID 41156185, 2025). "Consequently, PLWHA who are on Anti-Retroviral Therapy (ART) or Highly Active Anti-Retroviral Therapy (HAART) are usually predisposed to coronary artery diseases due to abnormal weight gain (lipohypertrophy), though with improved and unstable Cluster of Differentiation 4 (CD4) counts." (PMID 35029192, 2022). "Another study showed that expression of TIM-3+CD4+ T cells was increased in coronary heart disease patients as well and correlated with disease severity." (PMID 40761788, 2025). "A single-cell, high-dimensional analysis of peripheral blood from humans with coronary artery disease highlighted predominantly significant cell-to-cell interactions between CD4 effector/memory cells and the intermediate monocyte subpopulation (iMo)." (PMID 39161605, 2024). "However, low values of CD4+ count, in the presence of a cluster of cardiovascular risk factors, may also explain in part the occurrence of coronary artery disease in these patients, and it is most likely that other molecular mechanisms may also be involved and are subject to further analysis." (PMID 37627941, 2023). "It has been demonstrated that a range of immune cells are relevant to the advancement of coronary artery disease, such as CD4 T cells, Treg T cells, neutrophils, and dendritic cells." (PMID 36222281, 2022). "As expected, the CMV-seropositive patients showed a higher CD4+CD28- T cells compared with the control patients with coronary diseases." (PMID 35111365, 2022). "Expression of PD-L1 on CD4+CD25+FOXP3+ regulatory T cells in peripheral blood is negatively correlated with the severity of coronary heart disease." (PMID 39050559, 2022). "Alvi et al4 found that history of cocaine use was associated with greater likelihood of appropriate ICD discharge even after adjustment for history of coronary artery disease, CD4 count, use of beta blockers, QRS duration and higher NYHA class (p = .011)." (PMID 33594682, 2021). "Although a pathogenetic role of CD4+CD28null T-cells in coronary artery disease and atherogenesis have been recognized, important issues have remained unresolved." (PMID 34289931, 2021). "Monocytes and neutrophils were markedly increased, and T cell CD8, T cell CD4 naive, T cell CD4 memory resting, and NK cell resting were significantly decreased in MI groups compared with stable coronary artery disease (CAD) groups." (PMID 34777632, 2021). "Of note, an increased systemic CD4/CD8 T cell ratio was recently found to be strongly and independently associated with coronary artery disease in elderly individuals." (PMID 33391278, 2020). "Studies have also found associations between low CD4:CD8 ratio and coronary artery disease, but were underpowered to consider mortality." (PMID 28903507, 2017). "Patients with cardiovascular diseases such as coronary artery disease (CAD) are associated with a compromised adaptive immune response, not only in CD4+T cells but also in CD8+T cells." (PMID 26751202, 2016). "The multivariable analysis showed that for PLWH, a history of coronary artery disease, cocaine use, and increased QRS duration were associated with an increased SCD hazard ratio, while increasing CD4 and beta-blocker use was associated with a lower SCD hazard ratio." (PMID 41166354, 2025).
coronary artery disease (continued). "Our previous study revealed that JKAP represses the CD4+ T cell from differentiating into Th1 and Th17 cells in vitro and in vivo and is negatively correlated with Th1 and Th17 cells in blood from patients with coronary heart disease." (PMID 41458980, 2025). "Furthermore, in our study, we found that macrophages play a crucial role in naive CD4+ T cells in healthy coronary artery disease." (PMID 39610972, 2024). "Consistently, accumulating evidence indicates that on evaluation of the feasibility of DCs and T cells as a diagnostic tool, the subsets of blood CD4+, CD8+, and CD4+CD25+Foxp3+T cells and the ratio of CD4 to CD8 cells hold promise as biomarkers of coronary artery disease." (PMID 32849502, 2020). "Of note, in this latter study, when assessing NADE by category, low CD4/CD8 ratio was associated with a higher risk of coronary artery disease but not of cancer." (PMID 27548257, 2016). "In coronary heart disease, there is a higher expression of TIM3 in CD4+ T lymphocytes in peripheral blood, along with an increase in the expression of the hematopoietic growth factor IL-7 in blood." (PMID 41325840, 2025). "The lower frequency of CD4+ T cells in CABG patients relative to donors and recipients suggests a general dysregulation of T-cell responses in ischemic heart disease, indicating disturbed immunological homeostasis." (PMID 41155153, 2025). "Intriguingly, macrophages from patients with coronary artery disease have elevated PD-L1 expression and blocking PD-L1 in response to VZV enhanced VZV-specific CD4+ T cell responses." (PMID 30870532, 2019). "We assessed whether the frequencies of CD4+LAP+ and CD4+CD25+ Treg cells were associated with age, lipid and lipoprotein fractions, fasting glucose, CRP, and the Gensini score which used to quantify the severity of coronary artery stenosis in patients with coronary artery disease (CAD)." (PMID 24385687, 2013). "Our findings demonstrate that a simple six-colour flow cytometry panel targeting CD45, CD3, CD4, CD57, CCR7, and CD45RA could provide robust discrimination among healthy donors and patients at different stages of coronary artery disease (iCAD vs. ASCAD)." (PMID 40508061, 2025). "We analyzed 41,782 single CD4+ T cell transcriptomes for sex differences in 16 women and 45 men with and without coronary artery disease and with and without DM." (PMID 36077273, 2022). "After adjustment for various confounders, coronary artery disease, cocaine use, no use of beta blockers, low CD4 count/unsuppressed viral load, low left ventricular ejection fraction, increased QTc duration, and wider QRS were all independently associated with SCD among the HIV‐infected patients." (PMID 33594682, 2021). "Levels of anti-HCMV IgG also positively correlated with both the percentage and absolute number of terminally differentiated CD8+ and CD4+ CD45RA+ CCR7- TEMRA cells, indicating that immunosenescence may participate in the development of coronary artery disease." (PMID 29988679, 2018). "A recent study found that CD155 is highly expressed on macrophages in patients with coronary artery disease (CAD), delivering negative signals to CD4+ T cells expressing CD96 and/or TIGIT receptors." (PMID 39926714, 2024). "However, there was no statistical difference of mCD100 on CD4+ T cells between healthy individuals and patients with coronary heart disease, which was in line with the findings in NSLCL patients, suggesting that the change of CD100 on T cells might be CD8 specific." (PMID 33593275, 2021).